ZNF799 (zinc finger protein 799)
Description:
May be involved in transcriptional regulation.
Synonyms: ZNF842; HIT-40; MGC71805; HIT40
Tractability: PROTAC: ubiquitination databases record sites on it.
Gene: Protein-coding gene on chromosome 19 (12,390,016 to 12,401,271, reverse strand). Ensembl gene ENSG00000196466.
Subcellular location: Nucleus
Subcellular location (Human Protein Atlas): Nucleoplasm; Centriolar satellite
Pathways (Reactome):
Gene expression (Transcription): Generic Transcription Pathway
Gene Ontology:
Molecular function: DNA-binding transcription factor activity, RNA polymerase II-specific; RNA polymerase II transcription regulatory region sequence-specific DNA binding
Biological process: regulation of transcription by RNA polymerase II; regulation of DNA-templated transcription
Cellular component: nucleus
Genetic constraint (gnomAD): Loss-of-function variants: 27 observed, 35.38 expected, observed/expected ratio (o/e) 0.76, 90% interval 0.56 to 1.05. The upper end of that interval is the gene's LOEUF score, 1.05, which puts it in group 4 of 6, group 1 being the genes least tolerant of losing a copy. Missense variants: 699 observed, 735.03 expected, observed/expected ratio (o/e) 0.95, 90% interval 0.89 to 1.01. Synonymous variants: 210 observed, 243.34 expected, observed/expected ratio (o/e) 0.86, 90% interval 0.77 to 0.97.
Homologues: Orthologues: chimpanzee ZNF799 (98% identical), rat Zfp617 (31% identical), mouse Zfp961 (31% identical). Paralogues in human: ZNF443 (93% identical), ZNF823 (73% identical), ZNF442 (71% identical), ZNF44 (71% identical), ZNF441 (60% identical), ZNF563 (55% identical), ZNF700 (54% identical), ZNF709 (53% identical), ZNF433 (52% identical), ZNF14 (49% identical), ZNF791 (48% identical), ZNF878 (44% identical), and 3 more.
Diseases named in the same sentence as ZNF799 in open-access papers:
ZNF799 is named in the same sentence as 1 disease in open-access papers, as found by Europe PMC text mining. Sharing a sentence is not in itself a finding about the gene and the disease. The quoted sentences say what the papers report.
melanoma (1 paper, 2023). A malignant, usually aggressive tumor composed of atypical, neoplastic melanocytes. "The heatmap was used to demonstrate the expression levels of the genes TBX21, ZNF799, HEY2, ZNF580, IRF4, CREB3, and ZNF93 during the pseudotime trajectories of four distinct subtypes of melanoma cells." (PMID 37435067, 2023).